TGFB1 (transforming growth factor beta 1)
Diseases named in the same sentence as TGFB1 in open-access papers (continued):
Sharing a sentence is not in itself a finding about the gene and the disease.
emphysema (83 papers, 2004 to 2025). "In particular, polymorphisms in MMP9 and TGFB1 are proposed to protect against centrilobular emphysema, and polymorphisms in TIMP2 and TNF seem to increase the risk for paraseptal emphysema and/or airflow obstruction." (PMID 23734748, 2013). "In the current study, the TGFB1 rs2241718 SNP and a haplotype consisting of the rs1800469 and rs1800470 SNPs were found to be associated with centrilobular emphysema." (PMID 23734748, 2013). "Together with the MMP9 rs3918242 variant T-allele the TGFB1 rs2241718 variant A-allele reduced the risk of pathological centrilobular emphysema into fifth compared to the wild-type genotype." (PMID 23734748, 2013). "Of the genotypes examined, membership in cluster 1 (emphysema-predominant) was associated with TGFB1 SNP rs1800470." (PMID 20233420, 2010). "In contrast, the carriage of at least one TGFB1 rs2241712 variant A-allele was found to halve the risk for centrilobular emphysema (OR 0.53, 95% CI 0.30-0.90), as was also the carriage of at least one MMP9 rs3918242 variant T-allele (OR, 0.51 95% CI 0.30-0.86)." (PMID 23734748, 2013). "The association of the nonsynonymous Leu10Pro TGFB1 SNP rs1800470 with cluster 1 is consistent with a previously reported association of apical emphysema in this cohort and association of this SNP with reduced lung function has also been seen in a Japanese emphysema cohort." (PMID 20233420, 2010). "The core fucosylation is required for TGFB1 function as shown by data from Fut8 KO mice, whose emphysema-like phenotype can be explained by impaired TGFB signaling." (PMID 29462882, 2018). "The TGFB1 rs2241718 and MMP9 rs3918242 SNPs were associated with centrilobular emphysema (p = 0.022 and p = 0.008, respectively), and the TNF rs1800629 SNP was associated with paraseptal emphysema (p = 0.017)." (PMID 23734748, 2013). "The TGFB1 rs2241718 and MMP9 rs3918242 SNPs were associated with centrilobular emphysema (p = 0.022 and p = 0.008), and the TNF rs1800629 SNP with paraseptal emphysema (p = 0.017)." (PMID 23734748, 2013). "Results showed that the Has2+/− mice exhibited a more severe neutrophilic airway inflammatory reaction, higher degree of emphysema formation, and increased granulocyte-colony stimulating factor (G-CSF) with transforming growth factor beta 1 (TGF-β1) attenuation." (PMID 41181120, 2025). "Senescent cells secrete SASP mediators, such as MMP-12, TGFβ1, and IL-33, affecting the extracellular matrix homeostasis, which in combination with the loss of regenerative capacity of senescent AECII progenitors, leads to alveolar destruction and emphysema." (PMID 31428695, 2019). "The TGFB1 haplotype (rs1800469-rs1800470) was found to be associated with centrilobular emphysema (p = 0.018) (data not shown)." (PMID 23734748, 2013). "The previous studies on TGFB1 polymorphisms, COPD, emphysema, and related traits have provided contradictory results; some studies have found the variant alleles to predispose to emphysema and severe airflow limitation while others have found them to protect against COPD." (PMID 23734748, 2013).
thyroid cancer (82 papers, 2012 to 2025). "To better understand their role in the susceptibility and clinical features of thyroid cancer, we analyzed some TGFB1, TGFBR1, and TGFBR2 SNPs previously associated with human cancers as well as SNPs that have been implicated on gene and protein deregulation." (PMID 33905626, 2021). "The blockage of miR-19a/b with anti-miR restores TGFβ1 G1 cell cycle arrest in thyroid cancer cells." (PMID 26442266, 2015). "Indeed, in thyroid cancer, BRAF-mediated miR-17-92 up-regulation leads to a reduction of Smad4 and Tgfbr2 proteins and a loss of responsiveness to TGFβ1." (PMID 26442266, 2015). "DPP4 facilitates epithelial-to-mesenchymal transformation and thyroid cancer cell metastasis by interacting with α4 and β1 integrin subunits to activate the transcription of the TGFB1 protein via the FAK/AKT/C-JUN/TGF-β signaling pathway." (PMID 37470034, 2023). "In addition, METTL7B may also activate TGFβ1 and induce EMT in thyroid cancer." (PMID 34322156, 2021).
myeloma (80 papers, 2010 to 2026). "We also determined the expression of immune suppressive genes, and observed an increase in immune escape score and high expressions of CD47, LGALS1 and TGFB1 in low-immune response myeloma." (PMID 36717896, 2023). "We reasoned that this would mimic natural conditions since both multiple myeloma cells and bone marrow stromal cells (BMSCs) secrete high levels of TGFβ-1." (PMID 34945712, 2021). "Myeloma cell produce high levels of TGFβ1 (reviewed in 22, that potentially could up-regulate CD16 expression." (PMID 26029369, 2015). "Notably, hypoxia has been shown to promote myeloma cell dissemination from the bone marrow to the peripheral blood through the downregulation of E-cadherin and the upregulation of the epithelial to mesenchymal transition proteins SNAIL, FOXC2, and TGFβ1." (PMID 31020046, 2019).
acute kidney injury (79 papers, 2012 to 2026). Sudden and sustained deterioration of the kidney function characterized by decreased glomerular filtration rate, increased serum creatinine or oliguria. "Recent work from our group has demonstrated that combination therapy of paricalcitol and enalapril improved renal function and histology, suppressing the progression of renal failure via mediation/inhibition of the TGFβ-1 signaling pathway." (PMID 25300759, 2014). "The expressions of Tgfb1 and Havcr1, which increased in acute kidney injury, did not change significantly." (PMID 35633893, 2022).
lymphoma (78 papers, 2007 to 2026). A malignant (clonal) proliferation of B- lymphocytes or T- lymphocytes which involves the lymph nodes, bone marrow and/or extranodal sites. "Interestingly, the expression of TGFB1 appears to be increased in low-risk lymphomas, whereas its expression appears to be decreased in Peripheral T-cell lymphoma (PTCL)." (PMID 37925591, 2023). "These stromal cells are influenced by transforming growth factor-beta 1 (TGF-β1), which orchestrates myofibroblast differentiation, fibrotic remodeling, and Treg-mediated immunosuppression, thereby enabling lymphoma cells to evade immune detection." (PMID 40299416, 2025). "A study of a transgenic mouse model of Myc-driven lymphomagenesis demonstrates apoptotic lymphoma cells activate macrophages, leading them to secrete TGFB1, which drives lymphoma cell senescence." (PMID 35406544, 2022). "It is highly recommended that future studies could examine TGFB1 expression in specific subtypes of lymphomas and at a single-cell level." (PMID 37925591, 2023). "TGFB1 pathway activity was elevated in the ‘mesenchymal (MS) lymphoma microenvironment’ and reduced in the ‘depleted (DP) lymphoma microenvironment’, highlighting how TGFB may modulate local cellular composition." (PMID 35406544, 2022). "To confirm that this occurs through disulfide bonding to Cys33 in TGF-β1, we transfected human GARP and wild type (WT) or C33S mutant TGFB1 in murine BW5147 lymphoma T cells and in 293 cells as controls." (PMID 24098777, 2013).
neuroblastoma (77 papers, 2011 to 2025). Neuroblastoma (NB) is the most common solid, extracranial childhood tumor. "In fact, TGFB1 expression was detected in high-risk neuroblastoma tissues, and most neuroblastomas arise in adrenal glands that produce glucocorticoid." (PMID 38920727, 2024). "The microenvironment of high-risk neuroblastoma tumors includes macrophages, IL-6, and TGFβ1." (PMID 23982484, 2013). "We found that TGFβ-1, L1-70, and MIF were increased in the serum of old AD mice at 3 days after parabiosis surgery, and knock down of TGFβ-1 with siRNA in neuroblastoma cells decreased L1-70 and MIF expression along with the decrease in TGFβ-1." (PMID 35013124, 2022). "Functional assays with forced expression of miR-186 in neuroblastoma cell lines and NK cells, inhibited survival, and migration both in vitro and in vivo and prevented TGFB1 dependent inhibition of NK cytotoxicity." (PMID 36793342, 2022). "In order to further investigate the relationship between circulating TGFβ-1, L1-70, and MIF expression, mouse neuroblastoma N2a cells were transfected with TGFβ-1 siRNA." (PMID 35013124, 2022). "One target of miR-16 is Bcl-2; miR-186 from peripheral blood NK-derived exosomes has been shown to inhibit proliferation of neuroblastoma cells by targeting TGFβ1 and other proliferation genes." (PMID 34368150, 2021). "It has been shown that no single miRNA but the whole cluster mediated the repression of TGFB1-signaling in neuroblastoma cells." (PMID 29547527, 2018). "To further functionally confirm that TGFB1 is involved in directing neuroblastoma cell fate in a MYCN-dependant manner, we mined an RNAi knockdown screen targeting the druggable genome in SY5Y-MYCN cells." (PMID 28187790, 2017). "Among these, transforming growth factor beta-1, which is secreted by neuroblastoma cells, can promote the extravasation process by inducing actin cytoskeleton reorganization." (PMID 26500454, 2015). "IL-6, secreted by monocytes, and TGFβ1, secreted by neuroblastoma cells and monocytes, were shown to suppress IL-2 activation of NK cells." (PMID 26729169, 2015). "Since the suppression of NK cell activation by neuroblastoma/monocyte CM was likely due to IL-6 and/or TGFβ1, we next tested these cytokines alone and with lenalidomide to determine the effects upon NK cell activation." (PMID 23982484, 2013). "In summary, our study demonstrates that the microenvironmental milieu of neuroblastoma cells includes IL-6 and TGFβ1, which suppress IL-2 activation of NK cells for direct cytotoxicity, ADCC, and IFNγ secretion." (PMID 23982484, 2013). "Recombinant IL-6 and TGFβ1 were used at functionally effective doses to model the neuroblastoma/monocyte generated molecules to study the effects of these cytokines individually without or with lenalidomide upon NK cell activation." (PMID 23982484, 2013). "Neuroblastoma cell/monocyte co-cultures generated CM that contained IL-6 and TGFβ1 and that suppressed IL-2 activation of NK cells for direct cytotoxicity, ADCC, and IFNγ secretion." (PMID 23982484, 2013). "TGFβ1 was released into the culture medium by 12 of 15 well-characterized neuroblastoma cell lines, as assessed by ELISA analysis of CM after 72 h." (PMID 23982484, 2013). "Although the neuroblastoma/monocyte CM contained IL-6 and TGFβ1, these cytokines were increased further in cultures of NK cells and IL-2." (PMID 23982484, 2013). "CM from neuroblastoma/monocyte co-cultures contains IL-6 and TGFβ1 that suppress IL-2 activation of NK cell cytotoxicity and IFNγ secretion." (PMID 23982484, 2013). "IL-6, which is secreted by mononuclear phagocytes in response to neuroblastoma cells, and TGFβ1, which is secreted by both tumor cells and mononuclear phagocytes in response to neuroblastoma cells, suppress the activation of NK cells by IL-2." (PMID 23982484, 2013). "The TGFB1 signal was reduced in aggressive neuroblastoma tumors with high-expression of miR-17-92." (PMID 29547527, 2018).
neuroblastoma (continued). "TGFB1 was previously shown to be induced by RA in RA-responsive neuroblastoma cell lines." (PMID 28187790, 2017). "A subsequent study confirmed that higher levels of TAM-specific genes (CD14, CD16, IL6, IL6R and TGFB1) were associated with a worse prognosis in MYCN-nonamplified neuroblastomas." (PMID 26729169, 2015). "Because of these clinical and preclinical effects, we hypothesized that lenalidomide also could prevent the suppression of IL-2 activation of NK cells by neuroblastoma/monocyte CM, IL-6, and TGFβ1." (PMID 23982484, 2013). "Moreover, miR-17-92 was a potent inhibitor of TGFB1 signaling in neuroblastoma." (PMID 29547527, 2018). "These datasets revealed that TGFB1 was also a top regulator of the differences in the MYCN regulator and effector networks between single copy MYCN and MYCN-amplified neuroblastoma cell lines." (PMID 28187790, 2017). "A NOD/SCID mouse model of local disease was used in which CHLA-255-Fluc neuroblastoma cells were co-injected with PBMC (0.25 × 106) in 25 % (v/v) BD MatrigelTM Matrix Growth Factor Reduced, which includes TGFβ1." (PMID 23982484, 2013). "Directly downregulates MYCN and AURKA in neuroblastoma cells, which can potentially have a negative impact on their survival; miR-186 upregulation in NK cells resulted in the downregulation of TGFBR1 and TGFBR2 and, thus, impaired the TGFβ1-dependent inhibition of NK cells’ cytotoxicity." (PMID 33530529, 2021).
cardiomyopathy (76 papers, 2005 to 2025). A disease of the heart muscle or myocardium proper. "Upregulated DEGs were associated with pro-fibrotic signaling, such as TGF-β signaling-associated genes (TGFB1, LTBP1, ANKRD1) and other cardiomyopathy-related signaling, such as the MAPK cascade (ADRA1A, EGR1, IL6R)." (PMID 37084237, 2023). "Bones, tumors, and cardiomyopathy are examples of niches and conditions that contain MSCs and are enriched with tumor necrosis factor α (TNFα) and transforming growth factor β1 (TGFβ1)." (PMID 28553282, 2017). "In functional assays using a dual-luciferase assay system, mutant KLF15 showed neither transcriptional activation of the KChIP2 promoter nor transcriptional inhibition of the CTGF promoter, alone or in the presence of TGFB1, a key player in the pathogenesis of arrhythmias and cardiomyopathies." (PMID 33809104, 2021). "Intragenic-DMGs at 0.8% CO2 vs. 0.4% and 0.1% included: PDLIM7, whose resulting protein regulates valve annulus size and hemostasis; TGFB1, which regulates postnatal cardiomyocyte differentiation; and ILK, which has been shown to exhibit protective effects against cardiomyopathy." (PMID 33193638, 2020).
ischemia (75 papers, 2006 to 2025). A hypoperfusion of the BLOOD through an organ or tissue caused by a PATHOLOGIC CONSTRICTION or obstruction of its BLOOD VESSELS, or an absence of BLOOD CIRCULATION. "Finally, TSP1 was also found to contribute to the longer-term development of fibrosis after acute injury in an ischemia/reperfusion model, again associated with TGFβ1 activation." (PMID 36909183, 2023). "It was found effective in reducing hyperoxic stress-induced activation of the transforming growth factor-beta 1 (TGF-β1)/Smad2 signaling pathway in myocardial tissue following ischemia and reperfusion injury." (PMID 39765773, 2024). "Multiple microglia-related genes such as Cxcl10, Tlr7, Cd86, Tnfrsf1a, Nfkbia, Tgfb1, Ccl2 and Il-6, were upregulated with prolonged ischemia." (PMID 35154109, 2022). "We found that collagen type 1 alpha 1 and transforming growth factor beta 1 were substantially increased in untreated ischemia." (PMID 30148844, 2018). "We previously found that TGFβ1 expression is up-regulated in the damaged rat striatum in the first week after ICH or ischemia." (PMID 29780305, 2018). "Blocking TGFβ1 inhibited the phosphorylation of VEGFR2 and eNOS in EWT murine ECs, suggesting the hypothesis that endothelial NOX4 mediated ischemia-induced angiogenesis through TGFβ1-dependent activation of eNOS." (PMID 28587189, 2017). "Anti-inflammatory cytokines such as TGFβ1 and IL-10 have a beneficial function after ischemia." (PMID 22028848, 2011). "The results provided herein therefore support the possibility that the e-sEV-mediated activation of the TGFβ1/ALK1/ID1 cascade may provide a fine tuning angiogenic response which balances the vascular remodeling process and protects muscles against ischemia-induced damage." (PMID 28811546, 2017).
myopia (74 papers, 2008 to 2026). "Fourth, changes in Zc3h11a expression were found to cause changes in the myopia-related genes Tgfβ1, Mmp2, and Il6." (PMID 40864167, 2025). "CHRM3 and TGFβ1 have been implicated in the pathogenesis of myopia in Taiwanese individuals, while a high-myopia GWAS of Asian datasets identified the SNP rs6885224 in the CTNND2 gene on chromosome 5p15.2 as being associated with myopia." (PMID 39062192, 2024). "In the present study we evaluated polymorphisms in the LAMA1 (rs2089760) and TGFB1 (rs4803455) genes in children younger than 13 years of age with <6 D myopia in an attempt to further elucidate the genetic basis of high myopia." (PMID 29805427, 2018). "TGFB1 gene analysis in the high myopia group revealed heterozygous mutations in 32 patients (43.2%), homozygous mutations in 10 (13.5%), and no mutations in 32 patients (43.2%)." (PMID 29805427, 2018). "In conclusion, our study provides evidence linking inflammation-related gene polymorphisms—particularly in CCL2, TGFβ1, MMP1, and IL1β—to high myopia in children." (PMID 41138034, 2025). "In animal models of myopia, it has been established that intraocular concentrations of Tgfβ1 are elevated, especially in the retina and sclera." (PMID 40864167, 2025). "In age- and sex-adjusted allele-based tests, three loci were associated with high myopia: CCL2 rs2857656, TGFβ1 rs2317130, and MMP1 rs2071230 (P = 0.04, 0.03, and 0.04, respectively)." (PMID 41138034, 2025). "This network was composed primarily of genes involved in immune-mediated ECM remodeling, and included connections with many intermediate genes that have been strongly linked to myopia in previous targeted studies (e.g. MMP2, TGFB1, TGFB2, FGF2, INS, and IGF2)." (PMID 28852117, 2017). "TGFβ1 is expressed in the sclera and increases collagen production in scleral fibroblasts in a dose-dependent manner, a change that can also be observed during the progression of experimental myopia in animal models." (PMID 41138034, 2025). "In addition, the expression levels of myopia-related factors, such as Tgfβ1, Mmp2, and Il6, were upregulated in the retina and sclera of the Zc3h11a+/- mice." (PMID 40864167, 2025). "We did not require prior myopia association at selection; consequently, while a small subset of variants had been examined in myopia (e.g., TGFβ1 rs1800469), the majority were exploratory inflammation-pathway candidates (e.g., ETS-1)." (PMID 41138034, 2025). "Therefore, based on current evidence it was suggested that TGFB1 may contribute to some degree to the development of myopia." (PMID 29805427, 2018). "Numerous studies have investigated the role of TGFB1 and LAMA1, which are involved in the restructuring of scleral collagen and proteoglycans, in myopia." (PMID 29805427, 2018). "Furthermore, TGFβ1 may exert indirect proinflammatory effects through pathways such as TAK1–NF-κB, leading to downregulation of COL-1 and promoting the development of myopia and axial elongation." (PMID 41138034, 2025).